MMP19 (matrix metallopeptidase 19)
Description:
Endopeptidase that degrades various components of the extracellular matrix, such as aggrecan and cartilage oligomeric matrix protein (comp), during development, haemostasis and pathological conditions (arthritic disease). May also play a role in neovascularization or angiogenesis. Hydrolyzes collagen type IV, laminin, nidogen, nascin-C isoform, fibronectin, and type I gelatin.
Synonyms: MMP18; RASI-1; CODA
Tractability: Small molecule: it belongs to a druggable protein family. Antibody: its Gene Ontology location is reachable by antibodies, with high confidence; UniProt places it where antibodies can reach, with medium confidence; UniProt predicts a signal peptide or a membrane-spanning region.
Target class: Metallo protease; Metallo protease M10A subfamily; Metallo protease MAM clan; Protease; Enzyme
Gene: Protein-coding gene on chromosome 12 (55,835,433 to 55,842,968, reverse strand). Ensembl gene ENSG00000123342.
Subcellular location: Secreted, extracellular space, extracellular matrix
Subcellular location (Human Protein Atlas): Endoplasmic reticulum; Vesicles; Predicted to be secreted
Pathways (Reactome):
Extracellular matrix organization: Collagen degradation; Degradation of the extracellular matrix
Gene Ontology:
Molecular function: metalloendopeptidase activity; serine-type endopeptidase activity; metallopeptidase activity; zinc ion binding
Biological process: collagen catabolic process; extracellular matrix disassembly; extracellular matrix organization; proteolysis; luteolysis; ovarian follicle development; ovulation from ovarian follicle; response to cAMP; response to hormone
Cellular component: extracellular matrix; extracellular region
Genetic constraint (gnomAD): Loss-of-function variants: 47 observed, 46.8 expected, observed/expected ratio (o/e) 1, 90% interval 0.79 to 1.28. The upper end of that interval is the gene's LOEUF score, 1.28, which puts it in group 5 of 6, group 1 being the genes least tolerant of losing a copy. Missense variants: 588 observed, 661.05 expected, observed/expected ratio (o/e) 0.89, 90% interval 0.83 to 0.95. Synonymous variants: 222 observed, 255.83 expected, observed/expected ratio (o/e) 0.87, 90% interval 0.78 to 0.97.
Homologues: Orthologues: chimpanzee MMP19 (99% identical), macaque MMP19 (94% identical), pig MMP19 (86% identical), dog MMP19 (84% identical), guinea pig MMP19 (81% identical), rat Mmp19 (80% identical), mouse Mmp19 (79% identical), tropical clawed frog mmp19 (56% identical), zebrafish mmp19 (48% identical), Caenorhabditis elegans zmp-3 (25% identical), Caenorhabditis elegans zmp-4 (20% identical), Caenorhabditis elegans Y50D7A.13 (13% identical), and 2 more. Paralogues in human: MMP16 (33% identical), MMP24 (33% identical), MMP15 (33% identical), MMP14 (32% identical), MMP13 (31% identical), MMP10 (31% identical), MMP1 (31% identical), MMP17 (31% identical), MMP20 (30% identical), MMP3 (30% identical), MMP28 (30% identical), MMP25 (30% identical), and 11 more.
Diseases named in the same sentence as MMP19 in open-access papers:
MMP19 is named in the same sentence as 87 diseases in open-access papers, as found by Europe PMC text mining. Sharing a sentence is not in itself a finding about the gene and the disease. The quoted sentences say what the papers report.
glioma (8 papers, 2019 to 2025). A benign or malignant brain and spinal cord tumor that arises from glial cells (astrocytes, oligodendrocytes, ependymal cells). "For example, MMP-11 and MMP-19 have been observed to be upregulated in certain high-grade gliomas and are thought to participate in altering the physical properties of the ECM, enabling cancer cells to migrate more freely." (PMID 40265458, 2025). "Beyond these two genes, TNF Receptor Superfamily Member 18 (TNFRSF18) and Matrix Metallopeptidase 19 (MMP19), also selected by both methods, have been associated with a poor prognosis in glioma." (PMID 40428295, 2025). "And previous study had revealed that glioma patients with higher expression of MMP19 protein had shorter overall survival times, which was consistent with our findings." (PMID 35729639, 2022). "For example, OAS3 and MMP19 displayed higher expression levels in glioma samples compared to normal samples, recurrence samples compared to primary samples, high-risk group compared to low-risk group." (PMID 35729639, 2022). "Notably, genes such as LOXL1, IGFBP6, TNFRSF18 and MMP19, identified by both methods, have established links to glioma survival." (PMID 40428295, 2025). "MMP-12 has previously been associated with blood-brain barrier disruption via tight junction protein degradation after focal cerebral ischemia, while MMP-19 was associated with gliomas, but no studies had associated them with PNN formation or degradation." (PMID 37496706, 2023). "However, the high expression of MMP19 can also lead to the deterioration and poor prognosis of other tumors, such as colorectal cancer and glioma." (PMID 35069702, 2021). "MMP19 is highly expressed in astroglial tumors and promotes the invasion of glioma cells." (PMID 31088409, 2019). "These genes include HMGA1 in glioma, AKT1 in glioma, PTC, GC, and HCC, HEMGN in PTC, APLN and MMP19 in GC, WNT1 in CRC, NUPR1 in CRC and OSCC, LY6E and CTSB in CHOL, KLK4 and PLXNB2 in OC, and HDAC4 and STAT3 in SaOS." (PMID 36175921, 2022). "For example, bioinformatics analyses have shown that certain MMPs, such as MMP-1, MMP-11, MMP-19, and MMP-21, are consistently upregulated in GBM compared to normal brain tissue, suggesting that they may serve as biomarkers for diagnosis and prognosis in high-grade gliomas." (PMID 40265458, 2025).
melanoma (8 papers, 2008 to 2025). A malignant, usually aggressive tumor composed of atypical, neoplastic melanocytes. "MMP19 was strongly associated with melanoma (r = 0.593, p = 0.012), while PLXDC1 was associated with Leishmania infection (r = 0.581, p = 0.014) and ribosomes (r = −0.517, p = 0.033)." (PMID 39118664, 2024). "An increase in MMP19 expression indicates the progression of cutaneous melanoma and might augment melanoma growth by promoting the invasion of tumor cells." (PMID 31088409, 2019). "Recent studies based on mRNA and protein expression show that several MMPs, namely MMP-9, MMP-12 MMP-2, MMP-14, and MMP-19, play a role in melanoma aggressiveness and consequently may represent useful prognostic biomarkers." (PMID 30591049, 2018). "Recent reports show that MMP-19 expression is increased in melanoma, ovarian cancer and glioma." (PMID 24531055, 2014). "However, most of the melanoma associated antigens, including the MAGE genes, PRAME, S100A8, TRAG3 and MMP19, were more highly expressed in the MM samples than in NHEM." (PMID 18442402, 2008).
colorectal cancer (7 papers, 2019 to 2024). A primary or metastatic malignant neoplasm that affects the colon or rectum. "Emerging studies have discovered that STAT3, p300 and MMP19 are overexpressed in breast cancer, esophageal cancer, colorectal cancer (CRC) or NSCLC and so on, promoting cancer cell growth or metastasis." (PMID 38560562, 2024). "Finally, several matrix metalloproteinases (Mmp14, Mmp15, Mmp19), which are linked to poor prognosis of liver or colorectal cancer patients, are also upregulated by P2-HNF4α and dysregulation of genes involved in drug metabolism could impact treatment of liver cancer." (PMID 38111711, 2023). "This study implied that MMP11, MMP14, MMP17, and MMP19 are potential targets of precision therapy for patients with colorectal cancer." (PMID 34804973, 2021). "Chongshan Wu demonstrated that the high expression of MMP19 was determined to be a poor prognostic factor in colorectal cancer." (PMID 32850314, 2020). "Also, MMP11, MMP14, MMP17, and MMP19 are potential targets of precision therapy for patients with colorectal cancer." (PMID 34804973, 2021). "The transcriptional level of MMP17 and MMP19 in colorectal cancer tissue and normal tissue may need to be further confirmed." (PMID 34804973, 2021). "MMP1–MMP4, MMP7–MMP14, and MMP24 were significantly upregulated in colorectal cancer samples, while MMP15, MMP17, MMP19, and MMP24–MMP28 were significantly downregulated in colorectal cancer samples." (PMID 34804973, 2021). "Its expression has been demonstrated in some types of cancers, but the clinical significance of MMP19 in colorectal cancer (CRC) has not been reported." (PMID 31088409, 2019).
breast carcinoma (6 papers, 2009 to 2024). "Furthermore, for MMP-19 and -23 a significantly higher expression of the active protein could be observed in breast cancer tissue grade 2 when compared to normal breast tissue." (PMID 19531263, 2009). "This is certainly the case for MMP19, involved in the development of T cells in mice; MMP11, related to several cytokines in breast cancer cells; and ADAMTS1, a known regulator of the inflammatory response." (PMID 35903133, 2022). "At present, there are too few studies on MMP19 and breast cancer, and no clear conclusions have been formed." (PMID 35069702, 2021).
liver fibrosis (6 papers, 2012 to 2023). "Altogether, these data show that MMP-19 deficiency appears to impact the proteolytic network of MMPs during the development and recovery of liver fibrosis, reducing their potential to proteolyze ECM, especially in the initial phase of injury when components of the basement membrane are degraded." (PMID 23056273, 2012). "Thus, MMP-19-deficiency improves the development of hepatic fibrosis through the diminished replacement of physiological extracellular matrix with fibrotic deposits in the beginning of the injury, leading to subsequent changes in TGF-ß and IGF-1 signaling pathways." (PMID 23056273, 2012). "MMP-19 has also been found to be associated with hepatic fibrosis, and deficiency in MMP-19 has been shown to be associated with impaired TGF-β signaling and reduced liver fibrosis in the CCl4 murine model." (PMID 36777738, 2023). "MMP-19-/- mice showed reduced hepatic fibrosis via diminished ECM remodeling and accelerated liver regeneration regulated by TGF-β signaling pathway." (PMID 32414178, 2020). "MMP-19, also known as RASI-1, is widely expressed in the liver and has been associated with hepatic fibrosis." (PMID 32414178, 2020). "To assess the role of MMP-19 in liver fibrosis, we compared liver damage in MMP19KO and WT male mice after 4- or 6-week exposure to CCl4." (PMID 23056273, 2012). "In this study, we used MMP-19-deficient mice (MMP19KOs) to establish the role of this MMP in the development and resolution of liver fibrosis in mice using CCl4 intoxication." (PMID 23056273, 2012). "However, liver fibrosis is reduced in Mmp19−/− mice compared with wild-type controls, suggesting that MMP-19 is pro-fibrotic." (PMID 24713275, 2014).
pulmonary fibrosis (6 papers, 2015 to 2025). Chronic progressive interstitial lung disorder characterized by the replacement of the lung tissue by connective tissue, leading to progressive dyspnea, respiratory failure, or right heart failure. "We also found that the expression of ET1 in BLM-induced MMP19-AAV-infected mice and IPF lung was significantly higher than that in control lung tissues, which further indicated that MMP19-induced E(nd)MT and pulmonary fibrosis were associated with ET1." (PMID 36915092, 2023). "Finally, Clec4d and Mmp19 have been linked to pulmonary fibrosis, with Clec4d found to be highly expressed in lung tissue obtained from a mouse model of pulmonary injury and Mmp19 found to induce monocyte infiltration in human and mouse fibrotic pulmonary disease." (PMID 39056733, 2024). "For example, during pulmonary fibrosis progression, there was a notable increase in MMP19 expression in alveolar epithelial cells." (PMID 39993960, 2025). "In this study, we revealed the contribution of MMP19 in regulating E(nd)MT, monocyte infiltration and the pathogenesis of pulmonary fibrosis." (PMID 36915092, 2023). "To determine the role of MMP19 in pulmonary fibrosis, we generated mice that overexpressed MMP19 in the lungs by intratracheal injection of AAV and evaluated the response to BLM in MMP19WT- and MMP19E213A-AAV-infected mice." (PMID 36915092, 2023). "The regulatory mechanism of MMP19 in pulmonary fibrosis was elucidated by blocking its interacting proteins SDF1 and ET1 with AMD3100 and Bosentan, respectively." (PMID 36915092, 2023). "We found that AMD3100 inhibited MMP19-induced monocyte adhesion to HPMECs and CXCR4+ monocyte accumulation in lung tissues, and alleviated MMP19-induced exacerbation of BLM-induced pulmonary fibrosis." (PMID 36915092, 2023). "To further determine the role of ET1 in MMP19-induceded E(nd)MT, we evaluated the effect of BOS, which is an antagonist of the ET1 receptor, on MMP19-induced E(nd)MT and pulmonary fibrosis severity in the MMP19WT-AAV-infected mice after BLM instillation." (PMID 36915092, 2023). "Vascular integrity regulated by MMP19 could be a promising therapeutic target for suppressing pulmonary fibrosis." (PMID 36915092, 2023). "Mmp19−/− mice exhibited much more severe pulmonary fibrosis after BLM instillation than WT mice." (PMID 36915092, 2023). "Taken together, these results suggested that MMP19 aggravated BLM-induced pulmonary fibrosis." (PMID 36915092, 2023). "Thus, BOS inhibited MMP19-induced E(nd)MT and alleviated MMP19 mediated exacerbation of BLM-induced pulmonary fibrosis." (PMID 36915092, 2023). "MMP19 plays an important role in microvascular endothelial cell injury, activation and remodeling, and pulmonary fibrosis and could be a promising therapeutic target for suppressing pulmonary fibrosis." (PMID 36915092, 2023). "In addition, BOS significantly reduced the number of F4/80+ macrophages in MMP19WT-AAV-infected mice lung tissues, and alleviated MMP19-induced lung fibrosis, as evidenced by decreased hydroxyproline levels and collagen deposition in BLM challenged mouse lungs." (PMID 36915092, 2023). "In detail, deletion of MMP19 in mouse lungs accelerated the deposition of collagen, inhibited the repair of injured epithelial cells, and aggravated BLM-induced pulmonary fibrosis." (PMID 36915092, 2023). "It seems that MMP19 plays different roles in endothelial cells and epithelial cells in BLM-induced pulmonary fibrosis." (PMID 36915092, 2023). "We found that BOS inhibited MMP19-induced E(nd)MT and F4/80+ macrophage accumulation in lung tissues, and alleviated MMP19 mediated exacerbation of BLM-induced pulmonary fibrosis." (PMID 36915092, 2023). "MMP19 interaction with ET1 promoted epithelial‐to‐mesenchymal transition (E(nd)MT) and facilitated monocyte infiltration into lung tissue, worsening bleomycin (BLM)‐induced pulmonary fibrosis." (PMID 39993960, 2025).
pulmonary fibrosis (continued). "Thus, AMD3100 alleviated the MMP19-induced exacerbation of monocyte adhesion, infiltration and BLM-induced pulmonary fibrosis." (PMID 36915092, 2023). "Therefore, the enzymatic activity of MMP19 was crucial for enhancing the permeability of endothelial cells, promoting monocyte infiltration and aggravating BLM-induced pulmonary fibrosis." (PMID 36915092, 2023). "MMP19 promoted E(nd)MT by interacting with ET1 and stimulated monocyte infiltration into lung tissues via the SDF1/CXCR4 axis, thus aggravating BLM-induced pulmonary fibrosis." (PMID 36915092, 2023). "MMP19 promoted E(nd)MT and the migration and permeability of HPMECs in vitro, stimulated monocyte infiltration into the alveolus, and aggravated BLM-induced pulmonary fibrosis in vivo." (PMID 36915092, 2023). "Our previous study showed that silencing MMP19 significantly reduced epithelial cell migration and wound healing, indicating that the expression of MMP19 in epithelial cells is necessary for the recovery of injured epithelial cells and ameliorating BLM-induced pulmonary fibrosis." (PMID 36915092, 2023). "However, contrary to our initial hypothesis, increased expression of MMP19 could promote the degradation of ECM and inhibit pulmonary fibrosis." (PMID 36915092, 2023). "We found that AMD3100 significantly inhibited MMP19 induced monocyte adhesion to HPMECs and CXCR4+ monocyte accumulation in lung tissues, and alleviated the MMP19-induced increase in hydroxyproline levels and accumulation of ECM and collagen in BLM-induced pulmonary fibrosis." (PMID 36915092, 2023). "Thus, we hypothesized that endothelial cell-derived MMP19 promoted E(nd)MT, which led to the excessive accumulation of myofibroblasts in lung tissues and aggravated BLM-induced pulmonary fibrosis." (PMID 36915092, 2023). "Taken together, these results demonstrated that upregulation of MMP19 in endothelial cells promoted E(nd)MT and promoted the migration and proliferation of endothelial cell-derived fibroblasts by inducing E(nd)MT, and finally exacerbating BLM-induced pulmonary fibrosis." (PMID 36915092, 2023). "Therefore, we hypothesized that forced expression of MMP19 increased the activation and number of myofibroblasts in lung tissue, and aggravated BLM-induced pulmonary fibrosis by activating its effector cells." (PMID 36915092, 2023). "For instance, MMP-19 was shown to have adverse effects on fibrosis depending on the signaling pathway in some studies, and mice lacking MMP-19 showed more severe symptoms of IPF suggesting MMP-19 could act as a major regulator in pulmonary fibrosis." (PMID 32466129, 2020). "Our results showed that atorvastatin and ezetimibe could prevent HCD-induced lung fibrosis by downregulating the TGF-β-SMAD2/3 signaling pathway and enhancing MMP-19 expression, but not by modulating pro-fibrotic enzyme action." (PMID 37082028, 2022).
ovarian carcinoma (5 papers, 2014 to 2022). A malignant neoplasm originating from the surface ovarian epithelium. "We found that ovarian cancer cell lines with higher MMP-19 and MMP-20 protein expressing levels were more resistant to anti-cancer drugs, such as A-1210477 and Vincristine." (PMID 31406154, 2019). "These in vitro studies provided potential mechanisms of high MMP-19 and -20 expressions in the poor prognosis of ovarian cancer." (PMID 31406154, 2019). "ZEB1-AS1 promotes paclitaxel and cisplatin resistance by regulating MMP19 in ovarian cancer." (PMID 36246627, 2022). "Moreover, through experiments using ovarian cancer cell lines, we found cell lines with high MMP-19 or MMP-20 expression levels were more resistant to several anti-cancer drugs." (PMID 31406154, 2019). "Finally, knockdown of MMP-19 or -20 also decreased the invasion abilities of several ovarian cancer cell lines." (PMID 31406154, 2019). "Moreover, using in vitro studies, we found ovarian cancer cell lines with higher MMP-19 and -20 protein expressing levels were associated with anti-cancer drugs resistance, while knockdown of MMP-19 or -20 increased ovarian cancer cell sensitivities to several clinical using chemotherapy agents." (PMID 31406154, 2019). "Thus, our data suggests that overexpression of MALAT-1 might promote ovarian cancer progression by regulating the expression of MMP19, ADAMTS1 and MMP13 genes." (PMID 27227769, 2016). "MMP-19 and MMP-20 protein expression levels from six ovarian carcinoma cell lines (Ovcar5, Ovcar8, Cov362, Ov90, Ho8910 and Skov3) were assayed by western blotting." (PMID 31406154, 2019). "Triptolide, a compound extracted from the traditional chinese medicine preparation of Tripterygium wilfordii Hook F., can inhibit ovarian cancer invasion and tumor growth in vivo through transcriptional suppression of MMP-7 and MMP-19." (PMID 24531055, 2014). "Suppression of MALAT-1 resulted in downregulating the expression of MMP13 and up-regulating the expression of MMP19 and ADAMTS1 genes, indicating that MALAT-1 may involved in ovarian cancer by regulating the expression of the MMP13, MMP19, and ADAMTS1 genes." (PMID 27227769, 2016). "Nonetheless, based on our current data, we hypothesize that the efficacy of MALAT-1 in promoting ovarian cancer progression could be mediated by up-regulation of MMP13 and down-regulation of MMP19 and ADAMTS1." (PMID 27227769, 2016).